IDH1 (isocitrate dehydrogenase (NADP(+)) 1)
Diseases named in the same sentence as IDH1 in open-access papers (continued):
Sharing a sentence is not in itself a finding about the gene and the disease.
glioma (continued). "The more appealing targets for H3.3-G34 mutant gliomas are represented by PDGFRA, BRAF, and IDH1." (PMID 39202398, 2024). "We show that both VPA and the selective FASN inhibitor TVB-2640 rewire the lipidome and promote apoptosis in an IDH1 MT but not an IDH1 WT glioma cell line." (PMID 39149696, 2024). "IDH1 inhibitors are currently used in treating AML, gliomas, and solid tumours." (PMID 39340537, 2024). "That being said, our RCAS/Ntv-a Atrx KO model, though lacking mutant IDH1, closely mirrors the natural progression of low-grade gliomas in humans and corroborates the immunological effects of ATRX loss noted in human gliomas and the CT2A Atrx KO model." (PMID 38272925, 2024). "The activity of IDH1 enzyme in protecting CSC from oxidative damage has also been observed in glioma-initiating cells (GIC), where IDH1 inactivation, via silencing or pharmacological inhibition, diminishes NADPH production, reduces GSH levels, and increases ROS, thereby reducing GIC frequency." (PMID 36768660, 2023). "Switching to a focus on earlier stage disease, the phase III INDIGO trial is randomizing IDH1/2mt residual or recurrent grade 2, nonenhancing glioma to receive vorasidenib or placebo, with primary endpoint of PFS." (PMID 36968138, 2023). "IDH1 mutant gliomas without intratumoral microthrombi have the best prognosis, regardless of patient age." (PMID 37280670, 2023). "Another study showed that in contrast to IDH1-WT, neutrophils in IDH1-MUT glioma were not immunosuppressive, owing to increased expression of G-CSF by cancer stem-like cells as a result of epigenetic reprogramming." (PMID 36594465, 2023). "Although the results from these papers are promising, additional studies are required to establish if a vaccine against IDH1 R132H is effective in the glioma setting, where typically MHC II is not expressed." (PMID 37371615, 2023). "Under metabolic stress, FOXO1 increases Cyclin F but not other Cyclins in gliomas, suppressing IDH1 expression, an essential tumor marker which its overexpression is implicated in glioma progression." (PMID 37821870, 2023). "The dual IDH1/IDH2 inhibitor vorasidenib exhibited better brain permeability and target engagement than ivosidenib in a pilot perioperative randomized clinical trial in patients with IDH1-mutant glioma." (PMID 36823302, 2023). "Some existing molecular biomarkers, such as GFAP, IDH1 and Ki-67 antigen, are helpful for the diagnosis of molecular subtypes, individualized treatment and clinical prognosis of glioma, but their sensitivity and accuracy are still lacking." (PMID 37602882, 2023). "In addition to IDH1/2 mutation, MGMT promotor methylation, EGFR amplification, TERT promotor mutation, and CDKN2A/B homozygous deletion, we sought to elucidate the alterations of other potential molecular biomarkers that might provide clues for clinical decision-making in gliomas." (PMID 36998447, 2023). "This study highlights the non-canonical function of IDH1 in affecting epigenetic-inflammatory (PRMT1-PTX3) landscape in glioma to subsequently determine responsiveness to chemotherapeutics." (PMID 37476290, 2023). "For WHO grade 4 gliomas, the astrocytomas with IDH1-mut benefited when resecting the non-contrast-enhancing (NCE) tumor on the basis of resecting the contrast-enhancing (CE) tumor." (PMID 37029174, 2023). "Vorasidenib is an oral inhibitor of mutant IDH1 and IDH2 glioma cells, specifically designed for brain penetrance, which showed consistent suppression of D-2-hydroxyglutarate (2-HG), the oncometabolite that drives cell proliferation and favors brain-tumor related epilepsy." (PMID 38273856, 2023). "The aim of this study is to investigate whether cognitive functioning has a prognostic value for survival in patients with IDH1-wt, MGMT-unmet high-grade gliomas." (PMID 38168519, 2023).
glioma (continued). "Taken together these results indicate that the IDH1 mutant enzyme deacetylates histones and that the histone deacetylases may contribute essential and drug-targetable functions in IDH mutant glioma." (PMID 37528157, 2023). "Finally, we combined the results of the XGB model and univariate Cox regression analysis to identify age, FGFR2, IDH1, CDK4, CDK6, KIT, and CDKN2A as crucial predictors of prognosis and OS time for glioma patients." (PMID 37273702, 2023). "Interestingly, the PARP inhibitor sensitivity induced by mutant IDH1 is present and functional in both patient-derived AML and glioma cells." (PMID 37296846, 2023). "It is well known that wild-type isocitrate dehydrogenase 1 and 2 (IDH1 and IDH2, hereafter collectively referred to as IDH) and 1p19q non-deletion are two important genetic events in gliomas closely associated with rapid progression and high recurrence." (PMID 36969175, 2023). "Furthermore, we found that IDH1(R132H) decreased the transcription of IRF3/7 and downregulated the production of IFN-α and IFN-β in glioma cells." (PMID 37880243, 2023). "Isocitrate dehydrogenase-1 and 2 (IDH1 and IDH2) mutations have been described in several tumors, including gliomas, while in MB are rarely reported and not routinely investigated." (PMID 36941703, 2023). "Mutant IDH1 gliomas are classified as mutant IDH1-1p/19q-codel or mutant IDH1-noncodel, based on the deletion of 1p/19q chromosomal regions." (PMID 36146527, 2022). "Using the EPIC methylation array, which is a more robust array covering > 850,000 CpG sites, and a discovery cohort of 39 glioma tissue samples, we successfully developed a DNA methylation (CIMP) signature to specifically distinguish IDH1/IDH2-positive samples from IDH1/IDH2-negative samples." (PMID 36360312, 2022). "Interestingly, the recently published CATNON trial found no survival benefit of either concurrent or adjuvant TMZ among patients with IDH1 and IDH2 wildtype high-grade gliomas." (PMID 35804921, 2022). "Treatment of mice with the selective IDH1R132H inhibitor AG-5198 led to marked reduction of intracellular 2-HG levels and delayed the growth of IDH1-mut TS603 glioma xenografts (* p = 0.015, two-tailed t-test), without impairing IDH1-wt TS516 xenografts." (PMID 35267433, 2022). "Thus, the analysis of genomic alterations such as the isocitrate dehydrogenase 1 and 2 (IDH1, IDH2) and the histone H3 family 3A (H3F3A), HIST1H3B, and HIST1H3C genes as well as analysis of 1p and 19q status are now integrated aspects of glioma classification." (PMID 35453544, 2022). "In IDH-1 mutant gliomas, there is a higher NK-κB pathway activation, leading to NK cell migration in a CX3CL1-dependent manner, thus bringing a possible explanation for better outcomes observed in this setting compared to IDH-1 wild-type tumors." (PMID 36429101, 2022). "Cai’s group, for example, has developed a noninvasive 5-hmC detection method in circulating cell-free DNA of glioma patients, which was able to distinguish the difference between GBM and lower-grade gliomas regardless of IDH1 mutation status." (PMID 35494033, 2022). "For instance, AG-881, a chemical inhibitor of IDH1, is the foremost enhanced IDH inhibitor for grade II gliomas that have launched a phase III clinical trial with a significant outcome in this grade of gliomas." (PMID 35912242, 2022). "Indeed, even IDH1 and IDH2 gliomas, which are considerably more common than CS, are generally studied together because of their small numbers." (PMID 36042521, 2022).
glioma (continued). "IDH has three isomerase forms (IDH1/2/3), of which IDH1 and IDH2 are important indicators of glioma molecular classification, which are of great significance for the diagnosis, individualized treatment, and prognosis of gliomas." (PMID 35807084, 2022). "Nonetheless, the incidence, prognostic potential, and risk stratification significance of EZH2 expression in relation to IDH1 R132H protein mutant status and gliomas of various grades has not been fully elucidated." (PMID 36292072, 2022). "The low expression of miR-155 in IDH1-mutant glioma can upregulate the expression of FAM133A, which may further reduce the invasiveness and proliferation of IDH1-mutant glioma by targeting Matrix metalloproteinase-14 (MMP14)." (PMID 35677036, 2022). "Correspondingly, human GBM glioma tumors (IDH1-WT) with high oncostream densities showed prominent alignment of collagen fibers along these fascicles and higher COL1A1 expression compared to LGG (IDH1-Mut)." (PMID 35750880, 2022). "7/10 miRNAs studied here were more strongly expressed in glioma IDH1/2-WT (expression > 100) than in non-tumor brain tissue, while only 2/10 miRNAs were more strongly expressed in glioma IDH1/2-MUT than in non-tumor brain tissue." (PMID 35682718, 2022). "IDH1 wild-type glioblastoma (GB) is the most common malignant brain tumor, and the fifth edition of the World Health Organization (WHO) classification system classifies IDH1 wild-type gliomas as WHO grade 4." (PMID 35565263, 2022). "There were 10 patients who had histological diagnoses of glioblastoma WHO grade IV, 1 with glioma WHO grade III, 3 with R132H IDH1-mutated WHO grade II diffuse astrocytoma, and 2 with a diffuse astrocytoma that was IDH1-negative WHO grade II." (PMID 35448031, 2022). "Although clinical data on PARPi use in IDH1 mutated CCA is lacking, olaparib is currently being tested in patients with advanced glioma or cholangiocarcinoma with IDH1/2 mutations [NCT03212274]." (PMID 35626165, 2022). "Therefore, we included an extensive work up including the differentiation of high-grade versus low-grade gliomas and ATRX, IDH1/2, 1p19q, MGMT in our analysis." (PMID 34944806, 2021). "The IDH-wildtype astrocytic glioma classified as low-grade glioma MYB/MYBL1 by methylation profiling, was negative for IDH1/IDH2 and BRAF mutations by sequencing analysis and was 1p/19q non-codeleted." (PMID 33941250, 2021). "In gliomas, however, mutant IDH1/2 inhibitors have thus far not shown a survival benefit, but further studies on early-stage tumours are ongoing." (PMID 33740099, 2021). "IDH-mut glioma had better OS (p < 0.001) and PFS (p < 0.001) compared with patients without IDH1 mutation, which was in agreement with studies reported elsewhere." (PMID 34490090, 2021). "A Vorasidenib dose of 50 mg QD was selected and is under evaluation in the ongoing INDIGO study, randomized phase 3 in grade 2 non-enhancing IDH1/2 mutant glioma patients who have undergone surgery only (NCT04164901)." (PMID 34944036, 2021). "Overall, SLUG expression was significantly higher in GBMs than in the cortex and IDH1-mutant gliomas that did not harbor any, or very few, SLUG+ cells." (PMID 34771555, 2021).
glioma (continued). "Diffuse gliomas corresponding histologically to WHO grade 2 or 3 that are immunohistochemically negative for IDH1 R132H should be sequenced for less common IDH1 and for IDH2 mutations." (PMID 33293629, 2021). "The expressions of PLAU and PLAUR were evidently higher in higher WHO grade, recurrent gliomas, wild type IDH-1 and non-codeletion of 1p19q than their counterparts (p<0.0001)." (PMID 35087738, 2021). "It has been shown that treatment with CB839 radiosensitised IDH1 mutant cells in an in vivo model, resulting in tumour growth inhibition of IDH1 mutant gliomas but not of wild-type tumours." (PMID 34588983, 2021). "CSE inhibition sensitized these cells to cysteine depletion, an effect not observed in IDH1 wild-type gliomas." (PMID 34250481, 2021). "Our results demonstrate that application of scalp block, regardless of IDH1 profile, is an independent factor associated with longer PFS for patients with high-grade glioma." (PMID 34389754, 2021). "All patients had a confirmed diagnosis of IDH1-mutant glioma, which was recurrent or not responding to initial surgery, radiation, or chemotherapy." (PMID 34360713, 2021). "Our ‘all glioma’ analysis combined GBM, PA, and LGG in a cohort of a balanced numbers of tumors with and without the IDH1/2 mutation." (PMID 34206856, 2021). "GSDMD expression in glioma significantly correlated with clinical parameters, such as IDH1/2 wildtype, 1p19q non-co-deletion and mesenchymal subtype." (PMID 34830775, 2021). "Patients with IDH1 mutant and 1p19q codeletion exhibit better prognosis than those with IDH1-wild-type and 1p19q non-codeletion gliomas." (PMID 34925438, 2021). "Despite this, interest remains high and data from a Phase I study of Ivosidenib and Vorasidenib in patients with recurrent, non-enhancing, IDH1-mutant, low-grade glioma is currently pending." (PMID 33842321, 2021). "High grades, Isocitrate dehydrogenase 1 (IDH1) wide-type, 1p/19q non-codel gliomas represent poor prognosis." (PMID 34422904, 2021). "The results revealed that PACSIN1 had low expression levels in grade IV, IDH1 wild-type and 1p/19q non-codel group gliomas, and PACSIN1 was considered a mesenchymal molecular subtype marker." (PMID 34422904, 2021). "MutIDH1 glioma cells are likely reliant on GLUD2 for glutamate-dependent anaplerosis of the TCA cycle and express GLUD2 at significantly higher levels than WT IDH1 glioma." (PMID 35028610, 2021). "Surgical resection samples were obtained from ten glioma patients with grades II-IV including IDH1 positive and negative." (PMID 34150663, 2021). "IDH1 wild type GBM indicates higher malignancy and shorter survival time in glioma." (PMID 34458259, 2021). "WHO grading remained significant for OS in astrocytomas/IDH1-R132H-non-mutant gliomas (p < 0.01) but not for oligodendroglioma (p = 0.27)." (PMID 33538917, 2021). "Using the 5hmC-Seal technique, scientists identify healthy individuals from patients with WHO II-III gliomas and GBM and not be affected by glioma-related pathological features, such as Isocitrate Dehydrogenase [NADP (+)] 1 (IDH1) mutation." (PMID 34603383, 2021).
glioma (continued). "For 1p/19q non-codeleted IDH1/2mt gliomas, this difference is clinically relevant as patients harbouring non-R132H IDH1/2-mutated tumours have improved outcome." (PMID 33740099, 2021). "In grade II and grade III lower-grade gliomas (LrGGs), IDH1 wild-type group showed significantly lower ADC, D, f, DDC, α, and MD values (P < 0.05) and higher D∗, MK, and ICVF values (P < 0.05) than IDH1-mutant group." (PMID 34880724, 2021). "These indicated that IDH1 mutant might be related with the downregulation of MYD88 expression and less inflammatory responses in glioma TME, which could benefit the prognostics of glioma patients." (PMID 33898320, 2021). "Consistent with this, rs3761124 correlated with altered expression of RTEL1 in IDH1 wild‐type glioma and during early brain development but not in the CMC brain tissues." (PMID 33169458, 2021). "Furthermore, we took advantage of clinical human glioma samples to detect the protein pattern of BCAT1 and IDH1 R132H in glioma tissues." (PMID 33493139, 2021). "Glioma-related ctDNAs included 1p/19q, MDM2, ERBB2, IDH1, CDKN2A, CDK4, PDGFRA, CCNE1, MET." (PMID 32973641, 2020). "Although RSK2 protein expression do not increase during glioma progression, high RSK2 levels are associated with worse survival and RSK2 behaves as an independent prognostic marker when adjusted for IDH1 mutation status and treatment." (PMID 31701625, 2020). "In a recent phase I dose escalation trial of the IDH1 inhibitor ivosidenib, which included all glioma grades and enhancing as well as nonenhancing tumors, ivosidenib reduced the volume and growth rates of only nonenhancing tumors." (PMID 33396284, 2020). "Currently, the correlation between CXCR4/CXCR7 expression and IDH1 has been reported in human glioma but has not been reported in AML yet." (PMID 33381455, 2020). "Irrespective of IDH1 mutation, histogram parameters of Ktransand Ve were positively correlated with VEGF expression in gliomas (P < 0.05, respectively)." (PMID 33425744, 2020). "Moreover, the ctDNAs in the metastatic brain tumors included ALK and MDM2, and glioma-related ctDNAs included 1p/19q and MDM2 followed by frequencies of ERBB2, IDH1, CDKN2A, CDK4, PDGFRA, CCNE1, MET." (PMID 32973641, 2020). "The accumulation of BMDMs in the TME of IDH1 WT glioma was O6-independent of the methylation status of the O6-methylguanine DNA methyltransferase (MGMT) promoter." (PMID 33374253, 2020). "Here we screened 99 different malignancy grade astrocytomas for CASC2, and miR-21 gene expression by real-time quantitative polymerase chain reaction (RT-qPCR) in isocitrate dehydrogenase 1 (IDH1) and O-6-methylguanine methyltransferase (MGMT) assessed gliomas." (PMID 33120918, 2020). "In a feedback loop regulation, mutant IDH1 reduces HIF-1α-dependent TNC expression and decreases the aggressiveness of the gliomas through changes in the endothelial cells and the microglia and by promoting the acquisition of a mesenchymal stem-like phenotype by tumor cells." (PMID 32570988, 2020). "Although no targeted small molecules that can inhibit mutant IDH1 protein have been approved for glioma therapy, a number of inhibitors are still in early clinical phases." (PMID 32946483, 2020). "Specifically, it was the IDH1 mutant stable U87MG cells but not the mutant glioma tissue derived from patients that exhibited increased light chain 3 phosphatidylethanolamine conjugate (LC3-II) conversion." (PMID 32964017, 2020).